TNF (tumor necrosis factor)
Diseases named in the same sentence as TNF in open-access papers (continued):
Sharing a sentence is not in itself a finding about the gene and the disease.
optic neuritis (16 papers, 2011 to 2025). Optic neuritis is inflammation of the optic nerve, the nerve that carries the visual signal from the eye to the brain.The conditionmay cause sudden, reduced vision in the affected eye(s). "For example, is there a significant association between the anti-TNFα agents golimumab and certolizumab and the development of optic neuritis?" (PMID 39767762, 2024). "Another ocular adverse effect that was found to be consistently associated with anti-TNF-α therapy is optic neuritis." (PMID 32337619, 2020). "Similarly, optic neuritis and demyelinating peripheral nervous system disease was reported in association with the use of other anti-TNF agents." (PMID 39078559, 2024). "Optic neuritis is a serious complication that may lead to irreversible vision loss; therefore, patients being treated with a TNF-α antagonist should be closely monitored for the development of ophthalmological or neurological signs and symptoms." (PMID 32337619, 2020). "VPA treatment of optic neuritis, reduced optic nerve mRNA expression of TNF-α and Il-1β, inhibited upregulation of phosphorylated NF-κB p65 and downregulation of IκB suggesting a suppression of the NF-κB signaling pathway." (PMID 35646919, 2022). "Due to worsening non-neurologic disease, 4 patients were transitioned from etanercept to a monoclonal antibody against TNF, with a 5th transitioning to a monoclonal antibody following the development of optic neuritis while on etanercept." (PMID 35095905, 2021). "Of the individuals who had inflammatory demyelinating CNS events, 33 of 48 patients (69%) and 6 of 8 patients with optic neuritis (75%) were exposed to TNF inhibitors." (PMID 32421186, 2020). "Optic neuritis is a rare but well recognized serious adverse effect of treatments with tumor necrosis factor (TNF) antagonists." (PMID 22611506, 2011). "Utilizing the in vitro experimental model of optic neuritis standardized in our laboratory using the tumor necrosis factor-α (TNFα) as an insult, the current study investigated the neuroprotective properties of FTY in reducing the TNFα-induced injury in R28 cells." (PMID 34831161, 2021).
peripheral arterial disease (16 papers, 2011 to 2025). A disorder of the arteries supplying the upper and lower extremity and the visceral organs. "A clinical study showed that several inflammatory mediators including TNF-α are associated with poor clinical outcomes in peripheral artery disease." (PMID 35493949, 2022). "However, more recent studies have shown an association between elevated TNF-α levels and peripheral arterial disease." (PMID 21875436, 2011). "Overall, the results suggest that TNF-α plays a role in modulating exaggerated sympathetic nervous activity via the metabolic component of the exercise pressor reflex when the hindlimb muscles are ischemic in peripheral arterial disease." (PMID 30374312, 2018). "The aim of this study was to investigate the potential role of HMGB-1, OPG and several inflammatory mediators such as C-reactive protein (HsCRP), tumor necrosis factor-alpha and interleukin-6 (IL-6) on the presence and severity of peripheral artery disease in patients with T2D." (PMID 28789654, 2017). "Additionally, we also evaluated the association of adiponectin levels with fetuin-A and, respectively, TNF-α in patients with atherosclerotic peripheral arterial disease." (PMID 23819115, 2013). "In support of this theory, it was shown that the circulating levels of cytokines (IL-6 and TNFα), adhesion molecules (VCAM-1 and ICAM-1), and selectins in patients with peripheral arterial disease are elevated." (PMID 34447794, 2021). "In skeletal muscle, the expression of TNF-alpha, INF-gamma, IL-17A, IL-6, CCL5, and TGF-beta were increased in patients with peripheral arterial disease (PAD)." (PMID 36579591, 2022).
pyoderma gangrenosum (16 papers, 2006 to 2025). An idiopathic, rapidly evolving, and severely debilitating disease occurring most commonly in association with chronic ulcerative colitis. "Apart from JIA associated with IEI, TNF-alpha inhibitors have been used with good clinical efficacy in patients with 22q11.2DS with associated IBD and in one patient with XLA with associated pyoderma gangrenosum." (PMID 38468871, 2024). "Herein, we report a case presenting persistent large skin wounds as a diagnosis of pyoderma gangrenosum in the setting of IgA cutaneous vasculitis, which was successfully treated by a TNF-α inhibitor." (PMID 38577052, 2024). "We describe a case of pyoderma gangrenosum in a 16-years-old girl that arose after the administration of the TNF-α inhibitor adalimumab for CRMO." (PMID 37324147, 2023). "Additionally, a previous study has discovered that the TNF-NFκB pathway was upregulated in samples from patients with EN and pyoderma gangrenosum." (PMID 40038580, 2025). "Pathophysiologically, pyoderma gangrenosum is an autoinflammatory neutrophilic dermatosis marked by innate immune dysregulation, neutrophil hyperactivation, and overexpression of cytokines such as TNF-α, IL-1β, IL-17, and IL-23." (PMID 41440229, 2025). "However, some of these drugs, such as the anti-TNF-α agents (e.g., infliximab) and the IL-12/23 inhibitor ustekinumab, have been used successfully in other neutrophilic dermatoses, such as pyoderma gangrenosum." (PMID 37512497, 2023). "HS and pyoderma gangrenosum (PG) share clinical features, including similar demographic composition, presence of suppurating plaques and ulcers, neutrophil rich inflammation, response to tumor necrosis factor (TNF) inhibitors, and coexistence as part of autoinflammatory syndromes." (PMID 33493574, 2022). "For example, IL-1β is a potent inducer of TNFα, a major stimulant of apoptosis and inflammation, and an anti-TNFα monoclonal antibody, infliximab, has shown promising results in controlling symptoms of PAPA syndrome, including dramatic resolution of severe pyoderma gangrenosum in one patient." (PMID 21532836, 2010).
Q fever (16 papers, 2010 to 2024). A bacterial infection caused by Coxiella burnetii. "Theoretically, patients who are treated with anti-TNF-α medications are at risk for developing chronic Q fever." (PMID 27656302, 2016). "The use of interferon (IFN) and tumor necrosis factor (TNF) for chronic Q fever treatment has also been proven effective." (PMID 36013948, 2022). "We present herein a patient who developed acute Q fever under anti-TNF-α who had a good evolution after anti-TNF stoppage and treatment with doxycycline." (PMID 34158982, 2021). "Q fever patients with hepatitis show serum cytokines levels higher than those affected by pneumonia or fever, and TNF and IL-10 are increased in patients with valvulopathy and extremely high in case of endocarditis." (PMID 34796128, 2021). "Other cytokines also play a role in Q fever as TNF-α, IL-1-β, and IL-10 as well as IL-2 and the IL-12/IFN pathway does play a role." (PMID 32765448, 2020). "This was also the case for IL-1β when comparing QFS patients with CFS patients and asymptomatic Q fever seropositive controls, and TNFα when comparing QFS patients with CFS patients and healthy controls." (PMID 31088495, 2019). "We present two patients who developed Q fever while being treated with anti-TNF-α agents and discuss the significance of timely diagnosis of C. burnetii infection in these patients." (PMID 27656302, 2016). "In summary, infection with C. burnetii should be considered and specific serology testing performed in all patients being treated with anti-TNF-α therapies and suspicious for Q fever clinical presentation or with unexplained systemic symptoms." (PMID 27656302, 2016). "Timely diagnosis of Q fever in these patients should lead, in our opinion, to immediate cessation of TNF-α inhibitor and administration of proper antibiotic treatment." (PMID 27656302, 2016). "TNF-α mRNA and TNF-α protein levels are increased in C. burnetii re-stimulated monocytes of chronic Q fever patients compared to healthy controls." (PMID 25279829, 2014). "During this period, the anti-rheumatic treatment had been switched by the rheumatologist from etanercept to adalimumab (another anti-TNFα agent), and subsequently – 8 months after the acute Q fever episode – to rituximab." (PMID 24931640, 2014). "The circulating TNF and IL-6 levels were markedly increased in patients with acute Q fever compared with controls." (PMID 20594295, 2010). "Physiologically, acute Q fever patients show increased serological levels of TNFα and IL-6, whereas patients with valvopathy progressed to chronic infection have even higher amounts circulating TNFα and type I IFN, as well as reduced IL-1 receptor antagonist (IL-1Ra)." (PMID 38459007, 2024). "In C. burnetii antigen-stimulated whole blood, a high proportion of monocytes from both controls (Group 1) and IGRA-positive donors with a clinical history of Q Fever (Group 5) produced TNFα (median 10.8% and 17.6%), IL-1β (median 55.8% and 66.6%) and IL-6 (median 43.3% and 55.5%)." (PMID 37885896, 2023). "We present herein two patients who developed Q fever while receiving chronic anti-TNF-α treatment." (PMID 27656302, 2016). "Whether anti-Q fever vaccination of anti-TNF-α treated patients living in endemic areas can be of benefit needs to be examined." (PMID 27656302, 2016). "A particular subset of the population, namely, those who are treated by TNF-α inhibitors, might be at a disadvantage despite a paucity of reports on the prevalence and manifestations of Q fever in persons treated by anti-TNF-α medicines." (PMID 27656302, 2016). "In Q fever, IFN-γ promotes C. burnetii killing by the induction of TNF-mediated apoptosis in infected monocytes." (PMID 34796128, 2021). "In addition, it was suggested that RA and its treatment, either with or without anti-TNF, may be considered as a risk factor for chronic Q fever development, and it was advised to monitor RA patients carefully in case of C. burnetii infection." (PMID 26940462, 2016).
Q fever (continued). "The use of anti-TNFα agents for RA in the acute phase of Q fever does not seem to impede the C. burnetii-specific serological response." (PMID 24931640, 2014). "The use of anti-TNFα agents for RA in the acute phase of Q fever did not hamper the C. burnetii-specific serological response as measured by immunofluorescence assay." (PMID 24931640, 2014). "During the Dutch Q fever outbreak (2007–2010), our group demonstrated that QFS patients exhibit signs of altered immunity through the monocyte-derived cytokines Tumor Necrosis Factor (TNF)α, interleukin (IL)-1β, and especially IL-6, together with the interferon (IFN)γ-axis." (PMID 33243243, 2020). "In our hands, previous stimulation experiments of PBMCs with LPS for 24 h did not result in a difference in IL-6, TNFα, or IL-1β production between CFS patients, QFS patients, asymptomatic Q fever seropositive controls, and healthy controls." (PMID 31088495, 2019).
Respiratory tract infection (16 papers, 2018 to 2025). An infection of the upper or lower respiratory tract. "Lower levels of vitamin D promote the production of inflammatory transmitters, such as tumor necrosis factor-α and interleukin-1, which increase the risk of respiratory tract infection." (PMID 33167989, 2020). "TNF-α is an early inflammatory transmitter, which can impair the function of the upper respiratory tract in children, interfere with the immune regulation mechanism, and cause recurrent respiratory tract infections." (PMID 36619520, 2022). "In summary, in the treatment of inflammation caused by respiratory tract infections, the active components of PRHT play a key role through their synergistic actions with STAT3, TNF-α, and IL-6." (PMID 40456967, 2025). "There are only few published studies on respiratory tract infections under biologicals other than anti-TNF, such as anti-IL17, and most data are derived from clinical trials." (PMID 36389682, 2022). "And third, we saw that among those IBD patients, older age (>49 years) or taking TNF inhibitors, especially infliximab or ustekinumab, protected from respiratory tract infections." (PMID 36060521, 2022). "High concentration of IL-6, TNF-α, and IL-8 were found elevated in other cases of respiratory tract infections in different clinical settings in children (outpatients, inpatients, and intensive care units)." (PMID 33066100, 2020). "In addition to older age (>49 years), TNF inhibitors and ustekinumab show a protective role in preventing respiratory tract infections." (PMID 36060521, 2022). "Being older than 49 years and taking TNF blockers or ustekinumab might indicate a protective role in preventing respiratory tract infections." (PMID 36060521, 2022).
retinal diseases (16 papers, 2012 to 2025). "Overall, our data support a role for TNFα in inducing RPE damage and suggest that inhibiting TNFα directly or indirectly via targeting NA sensing may provide therapeutic benefit for patients with retinal diseases associated with inflammation-driven RPE degeneration." (PMID 37660150, 2023). "Four of the included studies reported the effects of resveratrol on TNF-α levels in animal models with retinal disease (experimental group, n = 25; control group, n = 25)." (PMID 40717982, 2025). "The roles of angiogenic and proinflammatory factors, including VEGF, TNF, TGFB1, CASP3, IL6, IFNG, and IL1B, and their association with miRNAs and the specified proteins in retinal diseases have been previously reported." (PMID 36180575, 2022). "The destructive role of TNF pathway in various retinal diseases and disorders like glaucomatous neurodegeneration is well documented." (PMID 33914756, 2021). "Among the inflammatory pathways enriched in our analysis, the IL6, JAK-STAT, TNFα, and NF-κB pathways exacerbate the pathology of retinal disease." (PMID 32735610, 2020). "This study shows the implication of TrkC.T1 in one of the most common inherited retinal diseases and uncovers the novel signaling mechanism of TrkC.T1–p-Erk–TNF-α production during disease progression." (PMID 29242588, 2017). "In the last few years, TNFα has been widely recognized as an attractive therapeutic target for the treatment of retinal diseases." (PMID 25301432, 2014). "Human umbilical vein endothelial cells or human aortic endothelial cells are the major endothelial cell types used in the literature for TNF-α induced adhesion assays, but only few studies have previously used retinal vascular cells to extend this approach to retinal diseases." (PMID 35579886, 2022). "Furthermore, cytokine inhibitors, such as TNF-α blockers (adalimumab, infliximab), IL-6 antagonists (tocilizumab), and IL-1β inhibitors (canakinumab), are being actively explored for their potential to reduce chronic inflammation in retinal diseases." (PMID 40722794, 2025). "Thus AAV-driven expression of human TNF-α mimics many aspects of human retinal diseases and may be used as a novel mouse model to further understand the pathophysiologic role of chronic TNF-α-related inflammation in the retina." (PMID 35579886, 2022). "Blocking TNF-α with monoclonal antibodies (e.g., infliximab, adalimumab) or soluble TNF receptors has been explored as a therapeutic approach in retinal diseases." (PMID 40722794, 2025). "Current data do not support the routine use of intravitreal TNF-α inhibitors in any retinal disease outside controlled trials." (PMID 22737386, 2012).
shigellosis (16 papers, 2011 to 2025). Shigellosis is a bacterial infection leading to dysentery and is caused by Shigella, which are small, ubiquitous Gram-negative bacteria belonging to the enterobacteria family. "To assess the in vivo role of TNFα during shigellosis, we first infected B6.Nlrc4–/– mice treated with an antibody that neutralizes TNFα, or with an isotype control antibody." (PMID 36645406, 2023). "The p-values were significant (<0.05) for IL-1β, IL-10, IFN-γ and TNF-α, but IL-2 and IL-4 levels were insignificant in shigellosis patients’ sera." (PMID 28767653, 2017). "In both animal models, S. flexneri induces the expression of proinflammatory cytokines, including IL-1β and TNF-α, as observed in humans suffering from shigellosis." (PMID 28650995, 2017). "It is known that high and sustained local intestinal levels of TNF-α and IL-6 are present during established shigellosis." (PMID 21818362, 2011). "The KEGG results indicated that differentially expressed Ex-mRNAs between the AW group and HCs were involved in Hematopoietic cell lineage (p = 0.0017), T cell receptor signaling pathway (p = 0.004), Shigellosis (p = 0.0058), and TNF signaling pathway (p = 0.0061)." (PMID 34489980, 2021). "In fact, significantly raised stool TNF-α has been detected in patients coursing shigellosis." (PMID 27774437, 2016). "Whereas the sustained elevation of TNF-α and IL-6 in saline treated mice corroborates with the massive tissue damage by the infiltrating monocytes or macrophages, an important characteristic of shigellosis, and ultimate death." (PMID 21818362, 2011). "Additionally, in CD8 TEM cells, CTL was identified in 2 of the 5 predominant MF groups; suggesting that CTL activity in combination with other cytokines (e.g., IFN-γ and TNF-α) could have an important role limiting shigellosis." (PMID 29534721, 2018). "NLRC4 appears to be both necessary and sufficient to protect mice from shigellosis, but in the absence of NLRC4, both Caspase-11 (even in the presence of Shigella effector OspC3) and TNFα can provide modest secondary protection." (PMID 36645406, 2023).